NPY6RP (neuropeptide Y receptor Y6, pseudogene)
Description:
When expressed, is unable to bind pancreatic polypeptide (PP), neuropeptide Y (NPY), or peptide YY (PYY), suggesting that either it is functionally inactive or that it may have acquired a pancreatic polypeptide-independent function.
Synonyms: PP2; NPY1RL; formerly NPY6R
Gene: Transcribed unitary pseudogene on chromosome 5 (137,808,211 to 137,809,322, forward strand). Ensembl gene ENSG00000226306.
Subcellular location: Membrane